Y_RNA (Y RNA )
Gene: Miscellaneous RNA gene on chromosome 1 (160,326,104 to 160,326,216, reverse strand). Ensembl gene ENSG00000202078.
Homologues: Orthologues: chimpanzee Y_RNA (100% identical), macaque Y_RNA (97% identical). Paralogues in human: RNY1 (91% identical), Y_RNA (89% identical), Y_RNA (87% identical), Y_RNA (86% identical), RNY1P11 (85% identical), Y_RNA (85% identical), Y_RNA (84% identical), Y_RNA (83% identical), RNY1P5 (82% identical), RNY1P8 (82% identical), Y_RNA (82% identical), RNY1P15 (81% identical), and 98 more.